TRBV6-2 (T cell receptor beta variable 6-2)
Description:
V region of the variable domain of T cell receptor (TR) beta chain that participates in the antigen recognition. Alpha-beta T cell receptors are antigen specific receptors which are essential to the immune response and are present on the cell surface of T lymphocytes. Recognize peptide-major histocompatibility (MH) (pMH) complexes that are displayed by antigen presenting cells (APC), a prerequisite for efficient T cell adaptive immunity against pathogens. Binding of alpha-beta TR to pMH complex initiates TR-CD3 clustering on the cell surface and intracellular activation of LCK that phosphorylates the ITAM motifs of CD3G, CD3D, CD3E and CD247 enabling the recruitment of ZAP70. In turn ZAP70 phosphorylates LAT, which recruits numerous signaling molecules to form the LAT signalosome. The LAT signalosome propagates signal branching to three major signaling pathways, the calcium, the mitogen-activated protein kinase (MAPK) kinase and the nuclear factor NF-kappa-B (NF-kB) pathways, leading to the mobilization of transcription factors that are critical for gene expression and essential for T cell growth and differentiation. The T cell repertoire is generated in the thymus, by V-(D)-J rearrangement. This repertoire is then shaped by intrathymic selection events to generate a peripheral T cell pool of self-MH restricted, non-autoaggressive T cells. Post-thymic interaction of alpha-beta TR with the pMH complexes shapes TR structural and functional avidity.
Synonyms: TRBV62; TCRBV13S2A1T; TCRBV6S2; TCRBV13S9/13S2A1T; TCRBV6S3; TRBV63; TRBV6-3
Gene: T-cell receptor variable (V) gene on chromosome 7 (142,349,152 to 142,349,664, forward strand). Ensembl gene ENSG00000283063.
Subcellular location: Cell membrane
Gene Ontology:
Biological process: cell surface receptor signaling pathway
Cellular component: plasma membrane
Homologues: Paralogues in human: TRBV6-1 (84% identical), TRBV6-5 (83% identical), TRBV6-7 (83% identical), TRBV6-8 (82% identical), TRBV6-6 (81% identical), TRBV6-4 (69% identical), TRBV10-3 (61% identical), TRBV10-2 (58% identical), TRBV10-1 (56% identical), TRBV27 (56% identical), TRBV24-1 (54% identical), TRBV28 (53% identical), and 39 more.